FOXM1 (forkhead box M1)
Diseases named in the same sentence as FOXM1 in open-access papers (continued):
Sharing a sentence is not in itself a finding about the gene and the disease.
prostate carcinoma (105 papers, 2005 to 2025). A carcinoma that arises from epithelial cells of the prostate gland. "SETD1A, which is expressed at a higher level in mCRPC than in primary prostate cancer cells, promotes the expression of FOXM1, a gene encoding a cell proliferation-specific transcription factor." (PMID 32629770, 2020). "Abnormal proliferative and invasive abilities are the phenotypes of cancer cells; we found the increased proliferative and invasive abilities in prostate cancers were possibly caused by FoxM1." (PMID 29554906, 2018). "In this report, we found increased mRNA level of FoxM1 was caused by c-Myc which was a new mechanism in prostate cancer." (PMID 29554906, 2018). "Here, the author show that that loss of miR-101 and miR-27a in prostate cancer cells can lead to COUP-TFII expression which in turn directly regulates FOXM1 and CENPF favouring prostate cancer metastasis." (PMID 27108958, 2016). "In high-risk group of patients and in lethal prostate cancers, Foxm1 mRNA was significantly overexpressed while SPDEF mRNA was significantly decreased." (PMID 25254494, 2014). "Expression levels of SPDEF and Foxm1 were compared between indolent and lethal prostate cancers and high-risk and low-risk sample groups." (PMID 25254494, 2014). "It is possible that the loss of SPDEF causes increased expression of oncogenic Foxm1, accelerating tumor cell proliferation and leading to poor outcome in prostate cancer patients." (PMID 25254494, 2014). "The over-expression of the FOXM1 transcription factor network has been associated with increased cell proliferation in animal models of prostate carcinoma." (PMID 23785426, 2013). "In cervical cancer, prostate cancer, and nasopharyngeal carcinoma, FOXM1 caused paclitaxel resistance by modulating the expression of ATP‐binding cassette subfamily C member 5 (ABCC5), in vitro and in vivo studies demonstrate that FOXM1‐specific inhibitors significantly weaken paclitaxel resistance." (PMID 41427004, 2025). "Altogether, the increased expression of FoxM1 in prostate tissues might be caused by c-Myc overexpression, and FoxM1 promoted the development of prostate cancer." (PMID 29554906, 2018). "Similarly, the same group showed that inhibition of OGT in the prostate cancer cell line PC3-ML was associated with an increase in FOXM1 degradation through a proteasome-mediated process." (PMID 23964270, 2013). "CENP‐F and FOXM1 serve as crucial regulators of prostate cancer malignancy and are indicative of poor tumor survival and extensive metastasis." (PMID 40387105, 2025). "Recent investigations have shown that the FOXM1 gene expression is upregulated in liver cancer, prostate cancer, colorectal cancer, et cetera." (PMID 41427004, 2025). "FOXM1 is a known major contributor to prostate cancer progression and its upregulation correlates with low disease-free survival, whereas KLF5 functions as a tumor suppressor and is downregulated in more advanced stages of cancer progression." (PMID 40115748, 2025). "FOXM1 TF is highly expressed in prostate cancer cells and contributes to cancer development and taxanes (paclitaxel or docetaxel) resistance." (PMID 38697979, 2024). "In prostate cancer, FOXM1 is highly expressed, and its regulation of EZH2 is essential for tumor cell proliferation and progression." (PMID 37686402, 2023). "Another EMT transcription factor FOXM1 induces docetaxel resistance in castration-resistant prostate cancer cells." (PMID 38062011, 2023). "FOXM1 knockdown induced cell apoptosis and G2/M cell cycle arrest, suppressing cell migration and invasion in docetaxel-resistant prostate cancer cell lines." (PMID 36798768, 2023). "An interesting study has demonstrated recently that FOXM1 transcriptionally activates RRM2 in prostate cancer." (PMID 36597126, 2023). "SPDEF also functions as a tumor suppressor in prostate cancer by inhibiting mRNA and protein levels of Foxm1, a transcription factor critical for tumor cell proliferation." (PMID 36809297, 2023).
prostate carcinoma (continued). "The results indicated that FOXM1 was largely expressed in castration-sensitive prostate cancer (CSPC) circulating tumor cells (CTCs) and castration-resistant prostate cancer (CRPC) circulating tumor cells (CTCs)." (PMID 35392496, 2022). "Zhou and colleagues demonstrated that TMP imparts cytotoxicity in prostate cancer cells through the inactivation of the DPP10-AS1/CBP/FOXM1 signaling pathway." (PMID 35883447, 2022). "This study provided novel insights into the regulation of prostate cancer distant metastasis by the exosomal HOXD-AS1 mediated miR-361-5p/FOXM1 axis, as well as a promising liquid biopsy biomarker for detecting and treating metastatic prostate cancer." (PMID 35172817, 2022). "NIC induces apoptosis in castration-resistant prostate cancer and reduces the growth of xenograft tumors by inhibiting the FOXM1-mediated DNA damage response." (PMID 36555754, 2022). "Prostate cancer cells actively absorbed exosomal HOXD-AS1, which acted as competing endogenous RNA (ceRNA) to alter the miR-361-5p/FOXM1 axis, driving prostate cancer metastasis." (PMID 35172817, 2022). "In another study, TMP was found to suppress cell proliferation and cell migration through downregulation of FOXM1 in prostate cancer cells." (PMID 35883447, 2022). "For example, the overexpression of FOXM1 synergistically with CENPF in prostate cancer leads to the activation of PI3K and MAPK signaling pathways, which are key signaling pathways involved in prostate cancer malignancy." (PMID 35392496, 2022). "In a recent study, SETD1A is proven to promote cancer stem cell property and castration resistance of prostate cancer cells by activating FOXM1 transcription." (PMID 34645486, 2021). "We recently described FOXM1 as a master regulator activated in highly aggressive prostate cancer patient subtype displaying neuroendocrine signature, and monensin as a novel FOXM1 inhibitor." (PMID 33572108, 2021). "This is consistent with the well-established role of FOXA1 as a major AR co-regulator and pioneer factor in prostate cancer cells, and the emerging role of FOXM1 in this capacity as well." (PMID 33513133, 2021). "The FOXM1 inhibition reduced stemness and growth of enzalutamide resistant prostate cancer tumors with stem and neuroendocrine-like phenotype in vivo." (PMID 33572108, 2021). "It has been reported that chicken ovalbumin upstream promoter-transcription factor 2 (COUP-TFII) promoted metastasis of prostate cancer through signal transduction of FOXM1 and CENPF." (PMID 33428600, 2021). "Some studies have found that CENPF and FOXM1 are major regulators in prostate cancer development; they synergistically promote prostate cancer malignant progression and metastasis." (PMID 35141213, 2021). "Most importantly, FOXM1, at high expression levels, is known to act as a driver of prostate cancer malignancies by synergistically interacting with CENPF." (PMID 32629770, 2020). "In prostate cancer, FOXM1 is required for the pathogenesis of prostate tumors, and its expression is regulated by MYC." (PMID 32629770, 2020). "The correlation between SETD1A and FOXM1 expression was verified in the human the prostate cancer gene expression data set." (PMID 32629770, 2020). "In prostate cancer, FOXM1 has been reported to regulate cancer stem cells (CSCs) through regulating UHRF1 gene expression and related taxane resistance." (PMID 32629770, 2020). "Although FOXM1 signaling was amplified in mCRPC, FOXM1 signaling also appeared to play an important role in LNCaP cells, an AR-dependent prostate cancer cell line." (PMID 32629770, 2020). "It was recently observed that CENPF and forkhead box M1 (FOXM1) cooperate together, acting as synergistic master regulators of malignancy in prostate cancer." (PMID 32973403, 2020). "We observed that the expression of both SETD1A and FOXM1 was increased in CRPC samples compared to that in primary prostate cancer in two independent clinical data sets." (PMID 32629770, 2020).
prostate carcinoma (continued). "Remarkably, hsa-miR-193 in prostate cancer was shown to target FOXM1 and RRM2, the last being one of the genes composing the prognostic 10-gene signature." (PMID 33333738, 2020). "c-Myc is known to regulate the expression of FoxM1 by binding to its promoter region in prostate cancer." (PMID 32429421, 2020). "First, it was confirmed that SETD1A, which is involved in the growth of various prostate cancer cells, was overexpressed in mCRPC and activates FOXM1 signaling during the progression of mCRPC." (PMID 32629770, 2020). "As a member of the forkhead box (Fox) transcription factor family, FOXM1 is acts as an oncogene in many tumors, such as breast, cervix, and prostate cancers, and is known to play crucial roles in the prognosis and chemoresistance of tumors." (PMID 31392101, 2019). "They found that reducing O-GlcNAc by shRNA inhibition of OGT in prostate cancer cells led to increased FoxM1 protein degradation." (PMID 31466420, 2019). "FoxM1 was an important regulator to the proliferative and invasive ability of prostate cancer cells which contributed to the development of prostate cancer." (PMID 29554906, 2018). "In this study, the increased mRNA level of FoxM1 and c-Myc in prostate cancer tissues was further confirmed." (PMID 29554906, 2018). "We found the expression level of FoxM1 was increased in prostate cancer tissues which was consistent with the reports of the other cancers." (PMID 29554906, 2018). "Compared with normal para-cancer tissues, the relative mRNA levels of FoxM1 and c-Myc were both increased in prostate cancer tissues." (PMID 29554906, 2018). "FoxM1 contributed to the pathogenesis of prostate cancer by regulating prostate cancer cells’ proliferative, invasive, and migratory abilities." (PMID 29554906, 2018). "In this report, the mRNA level of FoxM1 and c-Myc was detected in 30 prostate cancer and para-cancer tissues." (PMID 29554906, 2018). "In conclusion, we found increased expression of FoxM1 in prostate cancer samples compared with normal prostate samples." (PMID 29554906, 2018). "Wang and colleagues showed that increased FoxM1 expression is a target for metformin in the suppression of EMT in prostate cancer." (PMID 29416660, 2018). "Elevated expression of the transcription factor FoxM1 and c-Myc has been identified in prostate cancer." (PMID 29554906, 2018). "So, studying the other functions of FoxM1 in prostate cancer was important to fully understand its role in the progression of prostate cancer." (PMID 29554906, 2018). "Then, we mostly focused on the mechanism of the increased FoxM1 expression level to the pathogenesis of prostate cancer and the regulatory factors of FoxM1." (PMID 29554906, 2018). "To clarify the mechanism of the increasing expression level of FoxM1 in prostate cancer tissues, we tried to find the regulatory transcription factors of FoxM1." (PMID 29554906, 2018). "We found that the expression level of FoxM1 and c-Myc were both increased in prostate cancer samples compared with para-cancer samples." (PMID 29554906, 2018). "According to the transcription factor prediction in FoxM1 gene’s promoter, we focused on an important oncogene c-Myc which also increased in prostate cancer tissues." (PMID 29554906, 2018). "In prostate cancer (PCa), only few studies focused on the role of FoxM1; for instance, FoxM1 and its target CENPF, a structural protein of kinetochore, have been both proposed as critical drivers of PCa development and as prognostic markers of poor survival." (PMID 28770020, 2017). "This study clarified novel mechanisms by which prostate cancer becomes androgen refractory, and identified FOXM1 as a potential biomarker and therapeutic target in advanced prostate cancer patients." (PMID 28199985, 2017). "Inhibition of OGT expression has been shown to decrease the viability and invasion of prostate cancer cells through reduction of transcription factor FoxM1." (PMID 26824323, 2016).
prostate carcinoma (continued). "Cross-talk between the AKT pathway and the FOXM1 pathway has been demonstrated in osteosarcoma and prostate cancer." (PMID 26640950, 2015). "The present study identified novel crosstalk between SPDEF tumor suppressor and Foxm1 oncogene and demonstrated that this crosstalk is required for tumor cell proliferation during progression of prostate cancer in vivo." (PMID 25254494, 2014). "The combined two-gene signature of low SPDEF and high Foxm1 was a strong predictor of survival in prostate cancer patients." (PMID 25254494, 2014). "Altogether, these results indicate that SPDEF decreases proliferation and migration of prostate cancer cells through inhibition of Foxm1." (PMID 25254494, 2014). "Prostate cancers contain heterogeneous populations of cells including epithelial, inflammatory and stromal cells that enhances Foxm1 expression during carcinogenesis." (PMID 25254494, 2014). "The two-gene signature of low SPDEF and high FoxM1 predicted poor survival in prostate cancer patients." (PMID 25254494, 2014). "Our data demonstrate that SPDEF functions as a tumor suppressor in SV40 T antigens and c-Myc-induced prostate cancers by inhibiting tumor cell proliferation via disruption of an auto-regulatory element in the Foxm1 promoter." (PMID 25254494, 2014). "The FOXM1 pathway also regulates tumor metastasis (including that of prostate cancer) by stimulating the expression of several genes involved in the proliferation of tumor cells and cell cycle progression." (PMID 23782521, 2013). "More recently, the Reginato’s group showed that reducing O-GlcNAc in prostate cancer cells also reduced the expression of MMP2 and MMP9, associated with decreased FOXM1 expression." (PMID 23964270, 2013). "As a proto-oncogene, FOXM1 is highly expressed in various human cancers, promoting malignant cell proliferation in tumors such as gastric, breast, lung, pancreatic, colorectal, cervical, and prostate cancers." (PMID 40612352, 2025). "Regulation of prostate cancer cell senescence through the FOXM1/PCNA axis." (PMID 40458727, 2025). "More comprehensive studies are needed to confirm whether potential FOXM1/MYBL2/YAP pathway is responsible for regulating AR activity in response to changes in ECM stiffness in prostate cancer." (PMID 40115748, 2025). "These lncRNAs have been implicated in regulating various biological processes in prostate cancer through interactions with miRNAs, proteins, and other molecules Additionally, the regulatory role of exosomal HOXD-AS1-mediated miR-361-5p/FOXM1 in prostate cancer has been elucidated." (PMID 39090720, 2024). "FOXM1 and KIF20A exhibited consistent and highly correlated overexpression in prostate cancer cells and tissues, highly expressed FOXM1 may help promote docetaxel resistance by inducing KIF20A expression." (PMID 36798768, 2023). "The overexpression of FOXM1 and CENPF in prostate cancer have been linked to the loss of microRNAs such as miR-101 and miR-27a, to the synergistic cancer induction through the upregulation of PI3K and MAPK signaling pathways, and to the poor prognosis prediction of cancer patients." (PMID 36661515, 2023). "Furthermore, we detected the expression of FOXM1, a key modulator in prostate cancer progression and metastasis, as well as the most reported miR-361-5p target." (PMID 34864822, 2021). "The miR-877-5p is downregulated in prostate cancer tissues and cells, and its high expression of miR-877-5p attenuates cancer cell proliferation potential, migration abilities, and invasion capacity by targeting FOXM1." (PMID 34654353, 2021). "To explore whether miR-877-5p and FOXM1 can interact in prostate cancer, we used the DU-145 cell line, in which miR-877-5p has an especially high expression, to predict the relationship between FOXM1 and miR-877-5p." (PMID 34654353, 2021). "This conclusion further confirmed the important role of FOXM1 in prostate cancer." (PMID 34654353, 2021).
prostate carcinoma (continued). "In addition, the regulatory mechanism of miR-877-5P/FOXM1 in Prostate cancer was tentatively explored." (PMID 34654353, 2021). "Taken together, miR-877-5p may act as a suppressor in prostate cancer and reduces cancer cell proliferation, migration and invasion by targeting FOXM1." (PMID 34654353, 2021). "Then, the relationship between miR-877-5p and FOXM1 caught our attention, we speculated miR-877-5p may bind to FOXM1 to achieve the results of regulating cell biological function in prostate cancer." (PMID 34654353, 2021). "Recently, it is observed that FOXM1 expression has a potential prognostic value for prostate cancer, however, there is some evidence verifying that miR-877-5p can improve chondrocyte function of experimental osteoarthritis(OA) by targeting FOXM1 as a postulated molecular mechanism." (PMID 34654353, 2021). "FOXM1 was also identified as the downstream target of MYC in prostate cancer." (PMID 32210076, 2020). "Furthermore, FOXM1 has been observed to drive prostate cancer metastasis or malignancy by forming the COUP–TFII–FOXM1–CENPF cascade or by cooperating with CENPF." (PMID 32629770, 2020). "All these FoxM1 regulatory mechanisms in prostate cancer need further investigation." (PMID 29554906, 2018). "Next, we tried to identify whether FoxM1 could regulate the prostate cancer cells’ invasive and migratory ability." (PMID 29554906, 2018). "Both the increased expression of FoxM1 and c-Myc would promote the development of prostate cancer, and they might contribute to this disease by different mechanisms." (PMID 29554906, 2018). "The increase of FoxM1 and c-Myc expression was seen in 87.2% prostate cancer samples." (PMID 29554906, 2018). "c-Myc could regulate the expression level of FoxM1 by binding to its promoter region which was a newfound mechanism in prostate cancer." (PMID 29554906, 2018). "Further experiments showed that FoxM1 could promote the proliferative and invasive ability of prostate cancer cells." (PMID 29554906, 2018). "PC-3 cells were transfected with FoxM1 overexpression plasmid and interference RNAs to investigate whether FoxM1 could regulate the proliferative ability of prostate cancer cells." (PMID 29554906, 2018). "Finally, an inverse correlation between SPDEF and Foxm1 was found in human prostate cancers using two independent human prostate cancer microarray datasets, GSE21034 and GSE16560." (PMID 25254494, 2014). "Furthermore, an inverse correlation between SPDEF and Foxm1 levels was found in human prostate cancers." (PMID 25254494, 2014). "Therefore, understanding the mechanisms regulating Foxm1 is particularly relevant to the pathogenesis of prostate cancer." (PMID 25254494, 2014). "Since Foxm1 is up-regulated in mouse and human prostate cancers and is required for prostate carcinogenesis, we tested whether SPDEF inhibits Foxm1." (PMID 25254494, 2014). "Furthermore, re-expression of Foxm1 in SPDEF-expressing cancer cells restored tumor weight in orthotopic mouse model of prostate cancer, coinciding with increased number of Ki-67-positive and PH3-positive tumor cells." (PMID 25254494, 2014). "Our studies may serve as a foundation for the development of new therapeutic approaches in prostate cancer by targeting Foxm1 via SPDEF dependent pathways." (PMID 25254494, 2014). "Foxm1 is activated by the Ras/Erk signaling pathway and transcriptionally induces cell cycle-regulatory genes, including Cdc25b, Cyclin B1, Plk1, Aurora B. Recent studies demonstrated that Foxm1 is required for initiation and progression of various cancers, including prostate cancer." (PMID 25254494, 2014). "In addition, FOXM1 was checked as a direct target gene of miR-877-5p, and miR-877-5p can inhibit the expression of FOXM1 to restrain the growth, migration, and invasion abilities of prostate cancer cells." (PMID 34654353, 2021).